KIFC3 (kinesin family member C3)
Description:
Minus-end microtubule-dependent motor protein. Involved in apically targeted transport (By similarity). Required for zonula adherens maintenance.
Tractability: Small molecule: a structure with a bound ligand is known; a high-quality ligand is known. Antibody: UniProt places it where antibodies can reach, with medium confidence. PROTAC: ubiquitination databases record sites on it; its protein half-life has been measured.
Target class: Other cytosolic protein
Gene: Protein-coding gene on chromosome 16 (57,755,668 to 57,863,053, reverse strand). Ensembl gene ENSG00000140859.
Subcellular location: Cell junction, adherens junction; Cytoplasm, cytoskeleton, microtubule organizing center, centrosome; Cytoplasmic vesicle membrane
Pathways (Reactome):
Metabolism of proteins: Association of TriC/CCT with target proteins during biosynthesis
Gene Ontology:
Molecular function: protein binding; microtubule motor activity; ATP binding; microtubule binding
Biological process: epithelial cell-cell adhesion; zonula adherens maintenance; microtubule-based process; visual perception; microtubule-based movement
Cellular component: centrosome; extracellular exosome; mitochondrion; zonula adherens; kinesin complex; microtubule cytoskeleton; adherens junction; cytoplasmic vesicle membrane
Genetic constraint (gnomAD): Loss-of-function variants: 59 observed, 92.11 expected, observed/expected ratio (o/e) 0.64, 90% interval 0.52 to 0.8. The upper end of that interval is the gene's LOEUF score, 0.8, which puts it in group 3 of 6, group 1 being the genes least tolerant of losing a copy. Missense variants: 965 observed, 1,103.2 expected, observed/expected ratio (o/e) 0.87, 90% interval 0.83 to 0.92. Synonymous variants: 476 observed, 463.65 expected, observed/expected ratio (o/e) 1.03, 90% interval 0.95 to 1.11.
Homologues: Orthologues: chimpanzee KIFC3 (100% identical), macaque KIFC3 (99% identical), pig KIFC3 (96% identical), dog KIFC3 (96% identical), rat Kifc3 (94% identical), mouse Kifc3 (94% identical), guinea pig KIFC3 (91% identical), rabbit KIFC3 (90% identical), zebrafish kifc3 (53% identical), tropical clawed frog kifc3 (50% identical), Caenorhabditis elegans klp-3 (23% identical). Paralogues in human: KIFC2 (29% identical), KIFC1 (24% identical), KIF14 (21% identical), KIF13B (19% identical), KIF1C (18% identical), KIF1B (18% identical), KIF13A (18% identical), KIF1A (18% identical), KIF3A (18% identical), KIF3B (18% identical), KIF3C (17% identical), KIF16B (17% identical), and 29 more.
Diseases named in the same sentence as KIFC3 in open-access papers:
KIFC3 is named in the same sentence as 19 diseases in open-access papers, as found by Europe PMC text mining. Sharing a sentence is not in itself a finding about the gene and the disease. The quoted sentences say what the papers report.
breast carcinoma (7 papers, 2017 to 2023). "Overexpression of KIFC3 was shown to be associated with resistance to docetaxel in breast cancer cell lines." (PMID 37345113, 2023). "KIFC3 has been identified as a docetaxel resistance gene in breast cancer cells, however, the role of KIFC3 and its potential mechanism in colorectal cancer (CRC) remains elusive." (PMID 35812733, 2022). "In breast cancer, the overexpression of KIFC3 increased the resistance of breast cancer cells to docetaxel through opposing the microtubule stabilizing effect of docetaxel." (PMID 35812733, 2022). "Kinesins KIF1C and KIFC3 promotes breast cancer cell growth and survival and mediate taxane resistance." (PMID 32873298, 2020). "It has been reported that human KIFC3 is highly expressed in human docetaxel resistant breast cancers, and increases the amount of free tubulins in human breast cancer." (PMID 28977870, 2017). "KIFC3 has been identified as a docetaxel resistance gene in breast cancer cells." (PMID 35812733, 2022). "Previous work had shown that KIFC3 could play important roles in HCC invasion and metastasis, and increased KIFC3 expression levels had been associated with docetaxel- and paclitaxel-resistant breast cancer cells." (PMID 32414326, 2020).
osteosarcoma (2 papers, 2018 to 2025). A usually aggressive malignant bone-forming mesenchymal neoplasm, predominantly affecting adolescents and young adults. "In osteosarcoma metastasis, genes associated with chemokine activity, chemokine receptor binding, and the TNF signaling pathway are enriched, and KIFC3 has been identified as a significant prognostic biomarker." (PMID 40299423, 2025). "To further validate the transcript fusion between DAXX and KIFC3 in this sample we isolated RNA from both G292 cells and a telomerase positive osteosarcoma cell line, SJSA1." (PMID 30214690, 2018). "Some studies have also found that the expression of KIFC3 during osteosarcoma metastasis is positively correlated with follicular helper T cells, suggesting that KIFC3 may be involved in immune responses during osteosarcoma metastasis." (PMID 40299423, 2025).
colon cancer (1 paper, 2025). "Subsequently, in the GEPIA2 database, the expression level of KIFC2 in rectal cancer (READ) was significantly lower than that of the control group, while the expression level of KIFC3 in colon cancer (COAD) was significantly higher than that of the control group (p < 0.05)." (PMID 40299423, 2025).
diabetes mellitus (1 paper, 2023). A metabolic disorder characterized by abnormally high blood sugar levels due to diminished production of insulin or insulin resistance/desensitization. "Novel targets include MYO18A, SEC16A, CCNB1, MAD2L1, hsa-mir-4315, hsa-mir-6134, hsa-mir-9500, KIFC3, FBL (fibrillarin), TUBA1A and GFI1B might have crucial biologic functions in the pathogenesis of patients with diabetes mellitus and obesity." (PMID 36837510, 2023).
hepatocellular carcinoma (1 paper, 2022). A malignant tumor that arises from hepatocytes. "The high expression of KIFC3 suggests shorter survival time, and KIFC3 is associated with migration and invasion of hepatocellular carcinoma." (PMID 35812733, 2022). "Besides, KIFC3 was also found to be associated with hepatocellular carcinoma." (PMID 35812733, 2022).
pituitary adenomas (1 paper, 2025). "Additional genes—PHYHD1, LTBR, MYBPHL, C22orf42, PRR5, ANKDD1A, RAB13, CAMKV, KIFC3, WNT4, and STAT6—were implicated in the invasive behavior of non-functioning pituitary adenomas (NFPAs)." (PMID 39859246, 2025).
prostate adenocarcinoma (1 paper, 2020). "The probe chr16:57798350 located in the body region of KIFC3 was significantly hypomethylated in 12 cancers except for prostate adenocarcinoma." (PMID 32414326, 2020).
tumor (6 papers, 2018 to 2026). "We speculate that KIFC3 is specifically overexpressed in M1/M2 macrophages, and macrophage polarization is closely associated with the formation of an immunosuppressive tumor microenvironment." (PMID 40299423, 2025). "Meanwhile, in these cells, the expression almost exclusively occurred in tumor samples compared to control samples, indicating that KIFC3 plays an important role in the treatment of CRC." (PMID 40299423, 2025). "We analyzed gene expression data in the Oncomine and GEPIA databases to compare KIFC3 mRNA levels in the tumor and normal tissues from CRC patients." (PMID 35812733, 2022). "We found that the tumor growth rate was significantly slower in the KIFC3-depletion group than in the NC group (p < 0.001)." (PMID 35812733, 2022). "The results showed that LY294002 and Triciribine significantly attenuated the tumor-promoting effect of KIFC3 on CRC cells." (PMID 35812733, 2022). "Immunofluorescence staining revealed that the xenograft tumor tissues injected with sh-KIFC3 reduced the expression of KIFC3 and ki67, indicating the decrease of CRC cell proliferation." (PMID 35812733, 2022). "In a xenograft mouse model, the depletion of KIFC3 suppressed tumor growth." (PMID 35812733, 2022). "Then, we performed subcutaneous tumor formation experiments to verify the effects of KIFC3." (PMID 35812733, 2022). "Collectively, these findings elucidated that the down-regulation of KIFC3 could suppress tumor growth in CRC in vivo." (PMID 35812733, 2022). "The DNA methylation and expression levels of PHYHD1, LTBR, MYBPHL, C22orf42, PRR5, ANKDD1A, RAB13, CAMKV, KIFC3, WNT4 and STAT6 are associated with tumor invasion, and these genes may become the potential genes for targeted therapy." (PMID 31796052, 2019). "Moreover, KIFC3 was highly expressed in the CRC tumor samples." (PMID 40299423, 2025). "Furthermore, we detected the KIFC3 and ki67 expression on the tumor section." (PMID 35812733, 2022). "KIFC3 mediates PMM2-driven glycolysis, as KIFC3 knockdown partially reverses PMM2-induced metabolic reprogramming and tumor growth in xenograft models." (PMID 41786879, 2026).
cancer (3 papers, 2020 to 2025). A tumor composed of atypical neoplastic, often pleomorphic cells that invade other tissues. "KIFC3 was found to be associated with ECM receptor interaction, chemokine signaling, and cancer pathways." (PMID 40299423, 2025). "Low expression of KIFC3 may inhibit the transition of macrophages to a pro-cancer phenotype, thereby improving CRC prognosis." (PMID 40299423, 2025). "GSEA enrichment analysis was used to find that the main pathways in which KIFC3 is enriched include “ECM receptor intersection”, “chemokine signaling pathways”, and “pathways in cancer”." (PMID 40299423, 2025). "Additionally, based on the biomarker (KIFC3), the GSEA showed 88 KEGG pathways were detected, such as “Ecm receptor intersecting”, “chemokine signaling pathway”, and “pathways in cancer”." (PMID 40299423, 2025). "KIFC3 may be a promising biomarker that provides a new perspective into human CRC treatment, as well as targeting KIFs therapy seems to be a promising anti-cancer strategy." (PMID 35812733, 2022).
KIFC3 also shares sentences with these, for which no sentence is quoted: colorectal cancer (4 papers); cannabis dependence (1); cervical cancer (1); cone-rod dystrophy (1); infection (1); Obesity (1); Optic neuropathy (1); rectal cancer (1); retinitis pigmentosa (1); seminoma (1).